EEF1A2 (eukaryotic translation elongation factor 1 alpha 2)
Diseases named in the same sentence as EEF1A2 in open-access papers (continued):
Sharing a sentence is not in itself a finding about the gene and the disease.
myopathy (1 paper, 2013). A disease of the muscle in which the muscle fibers do not function properly. "eEF1A2‐null mutant wasted mice develop an aggressive, early‐onset form of neurodegeneration, but it is unknown whether the wasting results from denervation of the muscles, or whether the mice have a primary myopathy resulting from loss of translation activity in muscle." (PMID 24460877, 2013).
EEF1A2 also shares sentences with these, for which no sentence is quoted: bladder cancer (14 papers); bladder tumours (7); autism (5); developmental delay (3); gastrointestinal tumors (3); plasma cell neoplasm (3); prostate tumour (3); Ataxia (2); cardiac failure (2); colorectal adenocarcinoma (2); early-onset epileptic encephalopathy (2); endometrial cancer (2); esophageal cancer (2); myelogenous leukemia (2); Alzheimer disease (1); Angelman syndrome (1); asthma (1); autism spectrum disorder (1); brain injury (1); breast invasive carcinoma (1); brucellosis (1); Cerebral ischemia (1); cholangiocarcinoma (1); chronic cervicitis (1); chronic pancreatitis (1); colitis (1); colorectal (1); colorectal adenoma (1); dementia (1); epilepsy syndrome (1).
A further 54 diseases each share a sentence with EEF1A2 in 1 paper.